IL4 (interleukin 4)
Diseases named in the same sentence as IL4 in open-access papers (continued):
Sharing a sentence is not in itself a finding about the gene and the disease.
tumor (continued). "We further analyzed the production of IFN-γ, IL-4, IL17a, and Foxp3 in lymphocytes separated from the tumor tissues, which reflects the population of Th1, Th2, Th17, and Treg cells, respectively." (PMID 36209170, 2022). "The treatment with both vaccines under all regimens of therapy resulted in significantly lower IL4 production in all measured points compared to control tumor-bearing group." (PMID 35736195, 2022). "Mediators released by tumor-infiltrating lymphocytes, such as Th2 cells and Treg cells (producing IL-4 and Il-10), and by tumor cells (IL-10, TGFβ, and PGE2) activate an immunosuppressive program in TAMs." (PMID 35664746, 2022). "Tumor cell IL-4 staining was detected in 102 tumors (68%), with high expression observed in 75 patients." (PMID 35255925, 2022). "For example, Dong and colleagues described that fenretinide (4-HPR) significantly suppressed IL-4/IL-13 induced M2 polarization, resulting in fewer M2 macrophages in tumor tissues and dramatically decreased tumorigenesis." (PMID 35193986, 2022). "An additional qPCR analysis of the tumour cells showed significant increases in Il2, Ifng, Il1b, and Il18, and decreases in Il4, Il5, and Tgfb1, indicative of Th1‐dominant immune response." (PMID 35430766, 2022). "Among which, the expressions of anti-tumor cytokines including IL-2, IL-15 IL-17A, IFN-γ and TNF-α were up-regulated, while tumor-promoting cytokines including IL-4 and IL-10 were down-regulated in HER2.28ζ/PD-L1.BB CAR-T cells." (PMID 36402752, 2022). "The expression of IL4 in the tumor microenvironment can improve tumor growth and the blockade of IL4 can delay the growth and can also improve immunotherapies (in mice models) such as CpG ODN or anti-OX40 AB." (PMID 35565241, 2022). "Th9 cells are a recently identified subset of CD4+ T cells that produce IL-9 in response to TGF-β and IL-4 in vitro and have been shown to participate in the pathogenesis of allergic inflammation and asthma and play roles in anti-tumor immunity." (PMID 36241625, 2022). "Evaluation of the TME in vivo and IL-4 stimulation of macrophages in vitro suggested that SGR-EA delayed tumor progression by reversing the M2 polarization of TAMs and was associated with the inhibition of the HIF-1 signaling pathway." (PMID 35935838, 2022). "Several studies have shown that IL-4 serves as an anti-inflammatory cytokine in the tumor microenvironment." (PMID 35884700, 2022). "In vivo, SCL repressed the tumor growth by decreasing IL-4 and increasing IFN-γ level in breast cancer mice model, and notably suppressed the population of T regulatory cells (Treg) in tumor." (PMID 36263135, 2022). "IL-4 and IL-13 are believed to carry out abundant functions in tumour cells through several pro-oncogenic pathways involving signal factors such as STAT3, STAT6, PI3K/Akt, and ERK1/2." (PMID 35409019, 2022). "Together, these data suggest that IL-4 and IL-13 produced by ILC2s in the tumor niche promote M-MDSC-mediated suppression of anti-tumor immunity and IFNγ production, demonstrating the role of sustained innate signals in shaping the tumor microenvironment." (PMID 35658010, 2022). "Second, the group of cytokines were triggered in response to the resection procedure and then sustained in the newly regrown tumor (IL4, IL5, IL10, IL17, CCL2, IFN-γ and GM-CSF)." (PMID 35884700, 2022). "Monocytes from PBMCs were cultured in a medium with GM-CSF, IL4 and TNFα followed by pulsing with tumor cell lysate and treatment with 50% polyethylene glycol." (PMID 36011029, 2022). "Catalytic inhibitors of PARP14, such as RBM012042, can reverse IL-4 driven pro-tumor gene expression in macrophages." (PMID 35680848, 2022). "Once peripheral blood monocytes are recruited to the tumor, they rapidly differentiate into the M2 macrophages via induction of IL-4 and IL-10 derived from tumor cells, Th2-polarized CD4+ cells and regulatory T cells." (PMID 35210436, 2022).
tumor (continued). "Estrogen also appears to weigh the tumour immune balance towards tumour-promoting cytokines (IL-6, IL-4, TNF and IL-17A), M2 (pro-tumour) macrophage polarisation and diminished functional capacities of anti-tumour NK and CD8+ T cells." (PMID 36347875, 2022). "M-CSF can recruit monocytes to the tumor tissue where IL-4, IL-10, IL-13 and other factors present in the tumor microenvironment can induce the differentiation of monocytes into TAMs." (PMID 35741108, 2022). "M2 macrophage polarization has been linked to the production of IL-4, IL-10, TGF-beta and Granulocyte Colony Stimulating Factor (G-CSF) by tumour cells." (PMID 36531051, 2022). "The levels of IL-4, IL-10, and tumor markers (CA199, TSGF, and CEA) in the observation group were significantly lower than those in the control group (P < 0.05)." (PMID 36193493, 2022). "Tumor-associated macrophages (TAMs) are the predominant immune cell types with immunosuppressive M2 polarized phenotypes that secrete tumor cytokines (IL-4, IL-10, and IL-13)." (PMID 36479071, 2022). "The levels of IL-10, IL-4, and tumor markers in the observation group were significantly lower than those in the blank group (P < 0.05)." (PMID 36193493, 2022). "In contrast, Th2 cells secrete anti-inflammatory factors such as IL-4, IL-5, and IL-10 to weaken the anti-tumor immune response." (PMID 35646059, 2022). "Research has shown that IL-4 is involved in suppression of immunity against cancers, such that blockade of IL-4 leads to enhanced anti-tumor immunity, reduced tumor progression, and increased tumor-specific cytotoxic T lymphocytes." (PMID 35606804, 2022). "IL-4 and IL-13 are polarized to the M2 macrophage phenotype and support angiogenesis to drive tumor progression and recruit regulatory cells (Tregs)." (PMID 35800989, 2022). "Blocking IL-4 enhanced IL-12 production by tumor mregDC1s and expanded the pool of tumor-infiltrating T cells." (PMID 36275666, 2022). "CS inhibited tumor growth, also resulted in a decrease in interleukin-4 (IL-4) and IL-10 (IL-10) and an increase in interferon production." (PMID 35774546, 2022). "In our study, M2-polarized macrophages secreted significant amounts of IL-4, which are proposed to possess anti-inflammatory and tumor-promoting properties." (PMID 35960749, 2022). "In mouse models of bone metastasis, IL4 has also been shown to polarize bone MAMs (BoMAMs) to promote tumor growth." (PMID 36077870, 2022). "In contrast, the M2 phenotype is generally supposed to participate in immunosuppression and tumor promotion, which is formed after being exposed to macrophage colony-stimulating factor 1 (CSF-1), interleukin 4 (IL-4), IL-10, and IL-13." (PMID 36013403, 2022). "CD45+CD3+CD4+IL4+ T-cells were present in both FAK-wt and FAK−/− tumours at similar levels, and IL4 expression by these cells was also similar." (PMID 36138073, 2022). "It is established that the activation of Fcε RI on mast cells and basophils leads to secretion of interleukin 4 (IL4), which is an inducer of a tumor-suppressive macrophage subtype (M2 macrophage)." (PMID 35120484, 2022). "The IL-5 and IL-13 Th2 cytokines present in the tumor microenvironment of SS patients also favor eosinophilia, and IL-4 increases IgE." (PMID 35055124, 2022). "T cells recognize tumor antigens, activate and amplify effector T cells, and secrete cytokines such as IL-2, IL-4, IL-5, IFN-γ and granase to exert cytotoxic killing effects." (PMID 35729189, 2022). "Usually, M2 or alternatively activated macrophages are activated by IL-4, IL-10, IL-13, and glucocorticoid hormones, express high levels of IL-10 and low levels of IL-12, and facilitate tumor progression." (PMID 35928634, 2022). "The tumor cells in the lesional skin of the tumor-stage shift to a Th2 phenotype, which is characterized by the production of IL-4, IL-5, IL-10, and IL-13." (PMID 36295105, 2022). "It has been proven that IL-4 promotes tumor growth while also protecting tumor cells from autoimmune destruction." (PMID 35392217, 2022).
tumor (continued). "M2 macrophages secrete some anti-inflammatory factors, such as IL-4, IL-6, and IL-10, which negatively regulate the immune response in tumours." (PMID 35923703, 2022). "Th2 cells exerts their anti-tumor property by recruiting eosinophils through the expression of IL-4 and IL-13." (PMID 35155430, 2022). "STAT6 in vitro data suggested a role of the IL-4/STAT6 in disease relapse by providing a favorable niche for the clonogenic growth of tumor-inducing PCa cells." (PMID 35207527, 2022). "Inhibition of the CSF-1 pathway can be overcome by IL-4 stimulation of TAMs within the tumour microenvironment." (PMID 35359423, 2022). "Th1 cells produce tumor necrosis factor alpha (TNF-α), interferon gamma (IFN-γ), interleukin (IL)-2 and IL-12 to mediate antitumor effects, while Th2 cells produce IL-4 and IL-10 which favor tumor growth." (PMID 35805995, 2022). "Once in the TME, macrophage polarization can be driven by tumor cells, as well as by “tumor-educated” immune cells releasing M2-skewing factors such as IL-4, IL-13, immunocomplexes, transforming growth factor-β (TGF-β) or M-CSF." (PMID 36359283, 2022). "As expected, elevated levels of IL4 have been found in the sera of tumor-bearing mice produced by tumor-infiltrating lymphocytes and supporting activation of NF-κB in M2 macrophage phenotype." (PMID 35736195, 2022). "Th2 cytokine, IL-4, increased in tumor-bearing mice but decreased dramatically in PLAG and aPD-L1 treated mice." (PMID 35787261, 2022). "The cytotoxicity against tumor cells induced by GM/IL-4 DCs fused with QGP-1 (DC/QGP-1) was very low, while DCs loaded with another PC cell line elicited a high cytotoxicity of PBMCs." (PMID 35619702, 2022). "While Th2 cells secrete IL-4, IL-5, and IL-10 to promote polarisation of M2 macrophages, the positive interaction between the 2 cells constructs a tumour-suppressive immune microenvironment." (PMID 35591854, 2022). "A correlation was also observed between IgG4 staining and tumor expressed IL-10 (r = 0.0.488, p = 0.000), and IL-4 (r = 0.262, p = 0.001), as well as between IL-10 and tumor stage (IL-10 r = 0.254, p = 0.016)." (PMID 35255925, 2022). "For the first time, the correlation of the salivary levels of TNF-α, IL-1β, and IL-6 with HER2 status, MCP-1, IL-1β, IL-2, and IL-4 with the hormonal status of the tumor was shown." (PMID 36286034, 2022). "On the other hand, literature has shown that together with IL-1β or TGF-β, IL-4 can induce the differentiation of antitumor Th9 cells, inhibiting tumor growth." (PMID 36324671, 2022). "Macrophages are a heterogenous population of terminally differentiated monocytes that range in their function from pro-inflammatory and anti-tumor (M1 phenotype) to pro-tumor tissue remodeling (M2 phenotype), induced by IL-4, IL-10, IL-13, and CSF-1." (PMID 36223740, 2022). "Th1 cytokines, such as IL‐1β, IL‐2, IL‐12, IL‐18, TNFα, and IFNγ, are associated with proinflammation, while Th2 cytokines, such as IL‐4, IL‐5, and TGFβ, play a suppressive role in the tumour immune microenvironment." (PMID 35430766, 2022). "Conversely IL-4, IL-10 and IL-13 secreted by tumor or stromal cells can stimulate conversion of M0 to pro-tumor M2 macrophages." (PMID 36253762, 2022). "IL-13, structurally similar to IL-4, plays a role in tumor proliferation and metastatization and is considered a Th-2-derived protein." (PMID 35062739, 2022). "While type “M2” is induced by Interleukin-4 (IL-4) or Interleukin-13 (IL-13), and has a tumor-promoting effect." (PMID 36741415, 2022). "In contrast, the M2 phenotype is related to the immunosuppression in the tumor microenvironment by generating cytokines such as IL-4 and IL-13 and establishing a permissive environment for tumor progression." (PMID 35317079, 2022). "IL4 signaling in macrophages controlled the expression of CXCR2, which is necessary for IL4-mediated tumor cell extravasation in vitro." (PMID 36077870, 2022).
tumor (continued). "We differentiated these BMDMs for 6 days toward a pro-tumor (M2) phenotype using M-CSF, interleukin-4 (IL-4), and IL-10 and examined the effect of olaparib on these M2 macrophages." (PMID 36223740, 2022). "A main factor of type II NKT cells-mediated tumor immunosuppression is the increased production of IL-13 and IL-4 cytokines, which tilt immune response mainly toward the Th2 type with pro-tumor functions." (PMID 36119047, 2022). "By regulating IFN-γ and IL-4 signals, affects the polarization of pro-tumor macrophages and inhibits the antitumor inflammatory response." (PMID 35680848, 2022). "Although these TNBC-induced TAMs exhibit a differential gene expression profile, their tumor-promoting effects were similar to those of M2 macrophages polarized by IL-4 and IL-13." (PMID 35960749, 2022). "S9G), demonstrating that ILC2-derived IL-4 and IL-13 promoted the suppressive functions of tumor M-MDSCs." (PMID 35658010, 2022). "First, the effect of an exogenous source of IL4 on tumor cell transendothelial migration events in vitro in the presence of macrophages was measured." (PMID 36077870, 2022). "By blocking TGF-β signaling in CD4+ T cells, Th2 cells secrete IL-4, which reshapes the tumor immune microenvironment and suppresses tumor growth." (PMID 35684449, 2022). "In a high-throughput gene expression assay of HNSCC tumor, increased expression of IL-4 has been reported." (PMID 36376825, 2022). "The Th2 cytokine IL4 enhanced macrophage-dependent tumor cell extravasation in vitro while classical Th1 inflammatory signals inhibited this process." (PMID 36077870, 2022). "Following IL-4 blockade, the IL-12 production by tumor-antigen-bearing mregDC1s increased, favoring the expansion of tumor-infiltrating T cells and reduced tumor burden." (PMID 36275666, 2022). "Although many sources positively associate Tfh with survival, there are some instances where Tfh are reported to be detrimental to an anti-tumor response, correlated with Tfh production of IL-4." (PMID 35493515, 2022). "Consistently, in our previous study on BC, we found that the frequency of protumorgenic subtypes of CD8+ T cells producing IL-4 and IL-17, remarkably increased in the tumor-draining lymph nodes along with tumor progression." (PMID 36038861, 2022). "We next implanted 0.5 × 106 Panc47 FAK-wt and FAK−/− cells into the pancreas of C57BL/6 mice, culled mice 2 weeks post-implantation, and processed tumours for flow cytometry analysis to identify IL4+ CD4+ T-cells." (PMID 36138073, 2022). "IL-4, which shares its pathway with IL-13, is known to induce Lyve-1 and other LEC markers in tumor-recruited CD11b+ cells, whereas deficiency in IL-10 receptor (IL-10R) caused impaired lymphatic formation due to decreased generation of M2 macrophages." (PMID 35442077, 2022). "Our in vitro data suggest that IL4 signaling is relevant for extravasation and subsequent survival of tumor cells; however, the exact step requires elucidation in vivo." (PMID 36077870, 2022). "For example, tumor suppressor miR-195-5p inhibits GATA3-mediated secretion of IL-4 in CRC cells and ultimately M2-like tumor-associated macrophages polarization by suppressing the NOTCH2 expression." (PMID 35574420, 2022). "M2 macrophage can be induced to differentiate by IL-4, and promote tumorigenesis and tumor progression." (PMID 35757728, 2022). "Phosphorylation of STAT3 contributes to the deposition of collagen and release of IL‐10 and IL‐4 in tumours." (PMID 36178087, 2022). "In line with our data, BM-derived myeloid cells activated by IL-4/IL-13 upregulated lymphatic-specific markers Lyve-1 and stabilin-1 in several tumor models." (PMID 35442077, 2022). "We stained paraffin‐embedded sections of 100 CLL‐infiltrated and 100 tumour‐free lymph nodes for pSTAT6, an essential downstream target of IL4, and pIRAK4, a downstream target of TLR7/8/9." (PMID 35959629, 2022).
tumor (continued). "M2-polarization is indicated by Th2 cytokines such as IL-4 and IL-13 and leads to macrophage functionalization in the context of anti-inflammatory processes, tissue repair, and immunoregulatory and tumor-promoting processes." (PMID 35563052, 2022). "Tumor microenvironments in solid tumors are rich in many cytokines, including IL-1, IL-6, IL-4, IL-8, granulocyte-CSF, MF inhibitory cytokine-1 (MIC-1), and TGF-β, which can impair the anti-tumor immune responses and shield them from T-cell infiltration." (PMID 36627890, 2022). "M2 macrophages can be activated by IL-4 and IL-13 and are regulated by multiple transcription factors and secreted cytokines when regulating tumor growth progression, which inhibits immune response, hypoxia regulation, angiogenesis, invasion, and metastasis." (PMID 35874739, 2022). "Monocyte from PBMCs were cultured in a medium with GM-CSF and IL-4, followed by pulsing with hypochlorous acid (HOCl)-oxidized whole tumor cell lysate and maturation with LPS and IFNγ." (PMID 36011029, 2022). "COR inhibited tumor growth and elongated survival time of tumor-bearing mice by regulating the expression of cytokines such as IL-2, IL-4, TNF-α, TGF-β and IFN-γ." (PMID 35200422, 2022). "The same treatment caused IL-2 serum levels boosting (578 pg/ml) compared with untreated tumor-bearing mice that exhibited values of 185, 107, 30, and 52 pg/ml for IL-2, IL-4, IL-10, and IFN-γ, respectively." (PMID 35845806, 2022). "Mechanistically, ILC2-derived IL-4 and IL-13 in response to IL-25 signaling activated tumour M-MDSCs derived from Apc1322T/+ mice to express Arginase 1 (Arg1) and suppress CD8+ T cells." (PMID 36263033, 2022). "While the function of IL4 in the primary tumor has been well-studied, its role in metastases, particularly those of the lung, has not been explored." (PMID 36077870, 2022). "Monocytes from PBMCs were cultured in a medium with GM-CSF, and IL-4, and matured in TNFα, followed by pulsing with tumor lysate and Keyhole Limpet Hemocyanin (KLH)." (PMID 36011029, 2022). "In this type of tumor, macrophages produce versican V1 to induce a tolerogenic response mediated by the production of the type II cytokines interleukin-4 (IL-4), IL-5 and IL-10 due to the interaction of the hyalectan with antigen-presenting cells." (PMID 33804223, 2021). "Despite this, in an elegant series of experiments, they demonstrated that BM cells from tumor-bearing animals were able to be driven into differentiation into functional DCs when cultured in GM-CSF and IL-4." (PMID 33919157, 2021). "M2 macrophages, which are activated by the stimulation of IL-4, IL-13, or IL-21, are involved in wound repair, homeostasis, and tumor metastasis and tumor promotion." (PMID 33866463, 2021). "Remarkably, we observed increased nuclear NLRP3 expression in tumor lesions and during disease progression, which was also strongly correlated with IL-4 expression." (PMID 34220814, 2021). "This approach has also been used to improve antitumor activity in the TME by converting immunosuppressive signals, such as TGFβ and IL-4, into separate stimulatory signals that improve tumor selectivity and CAR T cell potency." (PMID 34177932, 2021). "TAMs created by a cytokine cocktail differ from both M(LPS) and M(IL-4) macrophages and co-express pro- and anti-inflammatory markers but eventually progress towards a pro-tumor phenotype." (PMID 34205266, 2021). "Increases in intratumor TFH that no longer control the HVEM-defective lymphoma clone can in turn support tumor growth through the secretion of IL-4 and other pro-lymphomagenic cytokines." (PMID 35071240, 2021). "This fused receptor is able to convert regulatory IL-4 signaling into IL-7 signaling and ultimately enhance the properties of CARs within the tumor microenvironment." (PMID 33855089, 2021). "IL-5 was significantly decreased in the tumours of the EE group compared to the SE group, IL-4 also showed a decreasing trend." (PMID 35008220, 2021).